IRS1 (insulin receptor substrate 1)
Diseases named in the same sentence as IRS1 in open-access papers (continued):
Sharing a sentence is not in itself a finding about the gene and the disease.
Insulin resistance (continued). "Chronic ER stress due to obesity induces adipose inflammation and suppresses signaling from the insulin receptor to insulin receptor substrate-1 (IRS-1), leading to insulin resistance." (PMID 32754041, 2020). "Brain insulin resistance is also observed to be developed early in DS subjects, as seen in the inhibition of IRS1 and the uncoupling of downstream elements of insulin signaling." (PMID 32825356, 2020). "Resistin diminishes the phosphorylation of AMPK and Akt pathways and decreases the production of IRS-1 as well as tyrosine phosphorylation of IRS-1, leading to increased insulin resistance." (PMID 32005271, 2020). "Subclinical inflammation in obesity has been associated with early insulin resistance brought upon by leptin-driven and increased levels of TNF-α and subsequent decrease in insulin receptor substrate 1 (IRS-1) signaling and tyrosine kinase activity." (PMID 32295104, 2020). "The reduced activity of Akt following insulin stimulation was associated with increased expression of serine 307 phosphorylation of the IRS1, a residue phosphorylation known to be related to insulin resistance." (PMID 33303821, 2020). "Conversely, an increased UA level inhibits insulin receptor substrate 1 and Akt and induces insulin resistance via augmented ROS production and oxidative stress." (PMID 33426022, 2020). "The up-regulation of miR-96 contributes to the development of insulin resistance by targeting insulin receptor substrate 1 (IRS-1) in SK-Hep1 cells." (PMID 33255227, 2020). "The excess of adipose tissue increases secretion of inflammatory cytokines such as TNF-alpha and IL-6 that inhibit phosphorylation of insulin receptors (IRS-1), promoting insulin resistance." (PMID 32599690, 2020). "Increased activation of muscle mTOR by nutrient overload or exposure to high insulin leads to increased serine phosphorylation of IRS-1, impaired insulin signaling and induction of insulin resistance." (PMID 32230718, 2020). "Oxidative stress upregulated miR-200a, which directly targets the 3'UTR of Insr and Irs1, leading to hindered insulin signaling and impaired insulin-dependent glucose uptake in skeletal muscle, ultimately promoting the development of insulin resistance." (PMID 32802189, 2020). "In the state of insulin resistance, IRS-1 serine phosphorylation inhibits insulin signaling by decreasing tyrosine phosphorylation, and thereby inhibits downstream effectors in insulin signal transduction, such as PI3K, Akt and GSK-3β." (PMID 31952248, 2020). "Heightened circulating LPS induces iNOS expression which promotes S-nitrosylation of Akt, IRS-1 and insulin resistance, deactivating nodes crucial to insulin signaling." (PMID 32429195, 2020). "This increase in fatty acid and cholesterol synthesis continuously causes insulin resistance, the activation of JNK, and the phosphorylation of IRS-1." (PMID 33312340, 2020). "PTP1B phosphorylates IRS-1 tyrosine residues, thereby impairing insulin signaling and inducing skeletal muscle insulin resistance." (PMID 32082422, 2020). "SOCS3, a known modulator of insulin resistance in the liver, is a protein induced by proinflammatory cytokines that directly inhibits IRS-1/IRS-2 by binding to specific sites, inhibiting phosphorylation and targeting the receptor substrates for degradation." (PMID 32315370, 2020). "For example, IRS-1 regulates insulin action in skeletal muscle as evidenced by findings that genetic ablation of IRS-1 results in insulin resistance and hypertriglyceridemia." (PMID 32610588, 2020). "Together, our findings suggest that this PNA model for PCOS results in hyperinsulinemia and skeletal muscle insulin resistance that is due in part to reduced Ser636/9 IRS1 and T389 p70S6K phosphorylation in some of the mixed composition hindlimb muscles." (PMID 33113794, 2020). "IRS-1 is a crucial adaptor protein that is phosphorylated at multiple serine and threonine residues by several kinases involved in insulin resistance." (PMID 32998286, 2020).
Insulin resistance (continued). "Reduced adipose tissue IRS-1 expression was reported in obese subjects, which impairs the downstream insulin signaling and the development of insulin resistance accompanied by increased adiposity." (PMID 32937828, 2020). "In human adipose tissue and skeletal muscle, a decrease in IRS1 levels has been described in a state of insulin resistance, although there are contradictory results." (PMID 31936857, 2020). "Our results support the notion that increased ceramide production by palmitate metabolism leads to activation of IKKβ and contributes to insulin resistance through inhibition of IRS1 in podocytes." (PMID 33303821, 2020). "The secreted cytokines TNFα and IL-6 cause insulin resistance in adipocytes through IKKβ and JNK1 kinase pathway activation, which interfere with insulin signaling via phosphorylation and subsequent IRS1 inactivation." (PMID 32878255, 2020). "Many studies showed that hyperphosphorylation/activation of mTOR and p70 S6K, results in increased serine phosphorylation of IRS-1 and contributes towards the development of insulin resistance." (PMID 32664532, 2020). "Multiple studies in rodent models of obesity and type 2 diabetes revealed the central role of IRS1 serine phosphorylation in the development of insulin resistance." (PMID 33303821, 2020). "Resveratrol, one of the most studied polyphenols, has been reported to restore the insulin receptor substrate 1 (IRS-1) and endothelial nitric oxide synthase (eNOSx) signaling pathway in endothelial cells under palmitate-induced insulin resistance." (PMID 32640649, 2020). "TNF-α induces insulin resistance by promoting lipolysis of adipocytes and increasing serine/threonine phosphorylation of insulin receptor substrate-1 (IRS-1)." (PMID 32337250, 2020). "Serine phosphorylation of IRS proteins is believed to be a major mechanism of suppression of IRS-1 activity that contributes to insulin resistance." (PMID 32210760, 2020). "Myostatin has been shown to induce insulin resistance by degrading IRS1 proteins and diminishing insulin-induced IRS1 tyrosine phosphorylation, thus interrupting insulin signaling cascade." (PMID 32831068, 2020). "Studies also showed that IR substrate-1 (IRS1) and IR substrate-2 (IRS2) expression were decreased, and the levels of inactivated serine-phosphorylated IRS1 were increased, resulting in insulin resistance in the brain." (PMID 32321934, 2020). "Increased activation of muscle mTOR by nutrient overload was shown to lead to increased serine phosphorylation of IRS-1, impaired insulin signaling, and induction of insulin resistance." (PMID 32664532, 2020). "As a potent antioxidant, ASX reportedly improved insulin resistance through the JNK-IRS-1-Akt axis by suppressing insulin-induced JNK phosphorylation and IRS-1 serine phosphorylation in the liver of HFD mouse." (PMID 32260306, 2020). "Serine phosphorylation is a major mechanism in suppressing IRS-1 activity that contributes to insulin resistance." (PMID 32210760, 2020). "In conclusion, our study demonstrates that increased levels of gWAT-derived exosomal miR-222 in the serum of obese model mice promote insulin resistance in the liver and skeletal muscle tissues by repressing IRS-1." (PMID 33197889, 2020). "TNF-α leads to insulin resistance by means of phosphorylation of serine residues of the insulin receptor substrate-1, preventing the receptor substrate from binding to the insulin receptor, and inhibiting insulin action." (PMID 32947869, 2020). "TNF-α and IL-6 can alter insulin sensitivity and stimulate the phosphorylation of serine residues instead of tyrosine in insulin receptor substrate-1 (IRS-1), thus inhibiting the activation of insulin signaling and sustaining insulin resistance." (PMID 32947869, 2020). "ER stress induces insulin receptor signaling through increasing the serine phosphorylation and decreasing the tyrosine phosphorylation of IRS-1 (IRSpY), leading to insulin resistance." (PMID 32180905, 2020).
Insulin resistance (continued). "The coupling of PI3K/Akt to IGF-1 and IR can be eliminated through serine phosphorylation of insulin receptor substrate-1 (IRS-1), mediated by mTOR, and IRS-1 inactivation and degradation, which is a prominent trigger of brain insulin resistance (BIR)." (PMID 33250703, 2020). "We previously proposed that IRS1 is more critical than IRS2 in insulin resistance–metabolic syndrome of the NTS." (PMID 32532282, 2020). "IRS-1 Ser phosphorylation is one of the mechanisms inducing insulin resistance in various tissues of patients and rodents with type 2 diabetes." (PMID 32444657, 2020). "Insulin receptor substrate (IRS-1) is an important target of the insulin signal transduction pathway in β-cells and plays an important role in the development of insulin resistance." (PMID 32774144, 2020). "As a result, various Ser kinases including JNK and PKC-θ are triggered, leading to IRS-1 phosphorylation on Ser, which results in insulin resistance." (PMID 33299532, 2020). "It has been shown in Tau knockout mice, that PTEN is activated, leading to neuronal insulin resistance through PTEN dephosphorylation of IRS1." (PMID 32236736, 2020). "Apart from indicating insulin-resistance and decreased glucose uptake, it suggests a relationship between IRS-1, tau (NFT) and Aβ pathology." (PMID 32655497, 2020). "At the same time, berberine also has a certain effect on the phosphorylation of IRS-1, which can finally alleviate insulin resistance." (PMID 32785222, 2020). "The most important mechanism of insulin resistance is that the increased FFA levels inhibit tyrosine phosphorylation of IRS-1, thereby inducing inactivation and inhibiting GLUT4 translocation to the cell surface, down-regulating insulin signaling." (PMID 33266423, 2020). "Numerous studies have established that serine phosphorylation of IRS-1 leads to impaired insulin action and contributes towards insulin resistance." (PMID 32230718, 2020). "This response is accompanied by local insulin resistance due to activation of kinases that phosphorylate serine residues of IRS1 and by excessive generation of ROS." (PMID 32604889, 2020). "Overexpression of MCP-1 in adipose tissue results in systemic insulin resistance and decreased tyrosine phosphorylation of the insulin receptor (IR) and IRS-1." (PMID 32842547, 2020). "Studies have shown that increased phosphorylation/activation of mTOR and/or p70 S6K leads to increased serine phosphorylation of IRS-1 and the development of insulin resistance." (PMID 32230718, 2020). "Phosphorylation of IRS-1 at serine 616 (pS616) and p-serine 636/639 are early markers of brain insulin-resistance, commonly present in MCI and AD." (PMID 32655497, 2020). "In combination with peripheral insulin resistance, there was also a report of an increased inhibitory phosphorylation of IRS-1 in serine 612 in the hippocampus of five-month-old tg2576 mice." (PMID 32365816, 2020). "IL-1α, IL-1β, and oxidative stress also induce insulin resistance by modulating IR or IRS-1 phosphorylation." (PMID 31581253, 2019). "Oxidative stress also induces insulin resistance by blocking relocation of IRS-1 and PIP (phosphatidylinositol)-kinase, promoting phosphorylation of IRS-1, and decreasing GLUT-4 expression." (PMID 31035653, 2019). "Increased production of TNFα and NEFAs by adipose tissue induces insulin resistance by suppressing tyrosine phosphorylation of IR or IRS-1, leading to abnormal metabolic activity in the liver, skeletal muscle, and adipose tissue." (PMID 31581253, 2019). "Altered IRS1 phosphorylation and insulin resistance have been reported in several tauopathies, including Alzheimer’s disease, progressive supranuclear palsy and corticobasal degeneration." (PMID 30606258, 2019). "In order to investigate the molecular mechanism by which HCQ enhances insulin resistance, the activation of Akt and IRS-1 was detected in liver tissue." (PMID 31427967, 2019).
Insulin resistance (continued). "In this analysis, cg21511036 (IRS1) was hypomethylated in subjects with hyperglycemia, insulin resistance and hypertriglyceridemia." (PMID 30926763, 2019). "Specifically, PA has been shown to induce insulin resistance and promote ubiquitination of key insulin signaling molecules such as IRS-1 and Akt." (PMID 31426858, 2019). "Pro-inflammatory cytokines such as, tumor necrosis factor-α (TNF-α), reduce the insulin-stimulated tyrosine phosphorylation of the insulin receptor and IRS-1, impairing insulin action and inducing insulin resistance." (PMID 30871083, 2019). "Other studies have noted the role of DAG activation of PKCθ in lipid-induced insulin resistance in muscle of obese individuals and individuals with type 2 diabetes, due to the effects on IRS-1 serine and tyrosine phosphorylations." (PMID 31179345, 2019). "IRE1α‐mediated activation of c‐Jun NH2‐terminal kinase (JNK) is thought to contribute to hepatic insulin resistance via phosphorylation and inhibition of insulin receptor substrate 1 (IRS1)." (PMID 31724300, 2019). "Our previous study has reported that WFA restores impaired insulin resistance in cultured endothelial cells by suppression of inflammation and thus prevents phosphorylation of IRS-1." (PMID 31226166, 2019). "Recently, seven markers based on the BMI-sensitive pathway of insulin resistance, adipoR1, adipoR2, ObR, IRβ, IRS-1, IGF-1R, and IGF-2R, have been proposed to develop a new molecular typing system for endometrial cancer." (PMID 31440472, 2019). "P-IRS1 (Ser307), a marker of insulin resistance, was increased in these animals, whereas the levels of Tyr632-phosphorylated IRS1 and Ser473-phosphorylated Akt were decreased with aging." (PMID 31246177, 2019). "As per the previous literature, TNF-α induces insulin resistance by inhibiting IRS-1 phosphorylation and GLUT-4 expression, and elevated in patients with heart failure, and myocardial ischemia reperfusion." (PMID 30674322, 2019). "Accordingly, we found that chronic treatment with atorvastatin induced insulin resistance of the IR/IRS-1/AKT pathway and through this mechanism increased proglucagon gene expression and glucagon secretion." (PMID 31546230, 2019). "Elements that reduce IRS-1 phosphorylation or activate serine IRS-1 phosphorylation at the 307 site cause defects in insulin signal transduction, ultimately resulting in insulin resistance." (PMID 31035653, 2019). "Pueraria lobate exerts anti-inflammation effects through regulating the IKKb/IRS-1 pathway and improving endothelial insulin resistance." (PMID 31871483, 2019). "Production of proinflammatory cytokines and suppression of IRS-1 has been documented as a primary progressive signaling node in the development of insulin resistance." (PMID 31551782, 2019). "Emerging data suggest that TNF-α, FFA and hyperinsulinemia, which induce insulin resistance, activate er307 phosphorylation on IRS-1 and inhibit its function." (PMID 30871060, 2019). "Meanwhile, PPAR δ inhibition improves LPS-induced lipid deposition and insulin resistance through regulating IRS-1/PI3K/AKT pathway." (PMID 31839747, 2019). "Chronic inflammation is a key triggering factor in the development of insulin resistance; pro-inflammatory cytokines can notably impair insulin receptor substrate-1 (IRS-1) signaling." (PMID 31717368, 2019). "In mature differentiated 3T3-L1 adipocytes naringenin treatment prevented the insulin-induced glucose uptake, reduced tyrosine phosphorylation of IRS-1 and reduced adiponectin levels, indicating induction of insulin resistance." (PMID 30871083, 2019). "High IRS1 phosphorylation at inhibitory serine residues is a general consensus marker of brain insulin resistance." (PMID 29736736, 2019). "IKKβ has been reported to induce insulin resistance through IRS-1 phosphorylation and inactivation, and this leads to the downregulation of Glut4, a regulator of glucose transport into the cell." (PMID 31616027, 2019).
Insulin resistance (continued). "Brain insulin resistance is characterized by increased activation of GSK3β and JNK, two critical kinases implicated in IRS1 inhibition." (PMID 29736736, 2019). "Decreased abundance of IR and elevated expression of Leptin, IRS1, and Glut4 have confirmed that continuous light impairs glucose metabolism and contributes to the insulin resistance in PCOS rat models." (PMID 32038578, 2019). "Prolonged hyperinsulinemia with excessive nutrition activates the mTOR/S6 kinase pathway, thereby enhancing IRS-1 serine phosphorylation to induce hypothalamic insulin resistance." (PMID 30875909, 2019). "Studies have suggested that a defect downstream of insulin receptor substrate-1 phosphorylation or PI3K activation is responsible for insulin resistance in some patients with PCOS." (PMID 31507635, 2019). "Studies have shown that TNF-α plays an important role in obesity-induced insulin resistance by promoting the serine phosphorylation of IRS-1." (PMID 30871060, 2019). "Here, 16% dietary SBP supplementation increased phosphorylation of both IRS1 and Akt, in line with a recent study showing that palmitoleic acid extracted from sea buckthorn alleviates insulin resistance through the Akt signaling pathway." (PMID 31022943, 2019). "Activation of insulin-dependent IRS-1-Akt-AS160 consequence was evaluated for the insulin-resistance according to increasing salt treatment." (PMID 30621146, 2019). "To investigate the effects of visfatin on insulin resistance, we evaluated insulin-signaling pathways, such as IR, IRS-1, GSK, and AKT using immunoblotting." (PMID 31396538, 2019). "Multiple systemic factors associated with insulin resistance, for example, free fatty acids and TNF-α, can reduce IRS-1 serine phosphorylation and thus inhibits its function." (PMID 30863203, 2019). "Abnormal serine phosphorylation or decreased expression of IRS-1 contributes to insulin resistance in the brain as well as in the peripheral tissues." (PMID 31723029, 2019). "Increased muscle DAG causes insulin resistance by activating PKC-θ and IRS-1 Ser-307 phosphorylation." (PMID 30717446, 2019). "Another point is that TNFα promotes insulin resistance through the phosphorylation of insulin receptor substrate 1 via the activation of cellular stress-responses kinases." (PMID 31349552, 2019). "In accord with the GLUT results, PPAR‐γ and IRS‐1 levels also responded to biotin and Cr supplementations in a similar way, improving insulin resistance." (PMID 30680172, 2019). "These serine kinases can alleviate the activation of IRS1, resulting in the impairment of insulin receptor-mediated signaling and the occurrence of insulin resistance." (PMID 31861309, 2019). "For further investigate the mechanism of TQPE preventing NAFLD, we detected the change of proteins expression including AMPK, SREBP, ACC, IRs-1 and Akt in the liver tissue, which were involved in lipid metabolism and insulin resistance." (PMID 31803542, 2019). "It has been observed in human hippocampal tissue that insulin resistance is accompanied by an increased phosphorylation at the Serine636 residues of IRS-1." (PMID 31427921, 2019). "Several studies demonstrated drugs that up-regulate IRS-1 expression exert the function of alleviating insulin resistance." (PMID 31723029, 2019). "Increased inflammatory cytokine expression resulted in serine phosphorylation of IRS1, which induced insulin resistance (IR)." (PMID 31699096, 2019). "Many of the polyphenols and flavonoids found in red sandalwood were previously reported to suppress inflammation and improve insulin resistance, which led to a recovery of IRS-1 expression." (PMID 31579450, 2019). "Accordingly, we found higher levels of inhibitory phosphorylation of insulin receptor substrate 1 (pIRS1Ser612), a marker of insulin resistance, in the ovaries of HFD-fed females (+54.7%, n = 7)." (PMID 31641124, 2019).